SNORD39 (Small nucleolar RNA SNORD55/SNORD39 )
Synonyms: LOC124900307
Gene: Small nucleolar RNA gene on chromosome 11 (109,263,494 to 109,263,564, reverse strand). Ensembl gene ENSG00000264997.
Gene Ontology:
Biological process: RNA processing
Cellular component: nucleolus
Homologues: Orthologues: chimpanzee SNORD39 (99% identical), guinea pig SNORD39 (55% identical), guinea pig SNORD39 (54% identical), tropical clawed frog SNORD39 (54% identical), tropical clawed frog SNORD39 (51% identical). Paralogues in human: SNORD55 (76% identical), SNORD39 (59% identical), SNORD39 (58% identical), SNORD39 (56% identical).